OR10G6 (olfactory receptor family 10 subfamily G member 6)
Description:
Odorant receptor.
Synonyms: OR10G6P; OR10G6Q
Tractability: Antibody: UniProt places it where antibodies can reach, with medium confidence; UniProt predicts a signal peptide or a membrane-spanning region; its Gene Ontology location is reachable by antibodies, with medium confidence.
Gene: Protein-coding gene on chromosome 11 (123,994,163 to 123,995,161, reverse strand). Ensembl gene ENSG00000198674.
Subcellular location: Cell membrane
Pathways (Reactome):
Sensory Perception: Expression and translocation of olfactory receptors
Gene Ontology:
Molecular function: olfactory receptor activity; G protein-coupled receptor activity
Biological process: detection of chemical stimulus involved in sensory perception of smell; G protein-coupled receptor signaling pathway
Cellular component: plasma membrane; membrane
Homologues: Orthologues: dog OR10G6 (90% identical), pig OR10G6 (87% identical), mouse Or10g6 (85% identical), rat Or10g6 (84% identical), guinea pig OR10G6 (58% identical). Paralogues in human: OR10G2 (54% identical), OR10G3 (52% identical), OR10G4 (51% identical), OR10G7 (51% identical), OR10S1 (51% identical), OR10G9 (50% identical), OR10G8 (48% identical), OR10D3 (46% identical), OR2D3 (44% identical), OR10C1 (42% identical), OR10A4 (42% identical), OR10A5 (42% identical), and 80 more.